AGT (angiotensinogen)
Diseases named in the same sentence as AGT in open-access papers (continued):
Sharing a sentence is not in itself a finding about the gene and the disease.
type 2 diabetes (continued). "Patients with type 2 diabetes have been shown to have lower SOD activity, a sign of higher oxidative stress, and catalase overexpression lowers the expression of angiotensinogen and apoptosis in diabetic mice." (PMID 38274131, 2024). "Previous studies reported that intrarenal angiotensinogen (AGT) mRNA and angiotensin (Ang) II levels were enhanced in type 2 diabetic rats." (PMID 29053707, 2017). "AGT expression is also increased in human biopsies with DKD and urine samples from people with type 2 diabetes and kidney disease." (PMID 24793984, 2014). "We therefore investigated associations of genetic polymorphisms in the AGT1R and AGT genes including AGT1R T573C, AGT1R A1166C, and AGT M235T and presence of CKD and CHD in type 2 diabetes." (PMID 19327134, 2009). "Visceral white adipose tissue (abdomen and upper body) appears to be the major source of inflammatory markers in type 2 diabetes (cytokines, TNF-alpha, IL-1, IL-6, IL-10, leptin, adiponectin, monocyte chemoattractant protein, angiotensinogen, resistin, chemokines, etc.)." (PMID 37298118, 2023). "Moreover, urinary AGT level reflects the activity of intrarenal RAS and tubular injury in patients with type 2 diabetes." (PMID 29053707, 2017). "We also found that in type 2 diabetes, treatment with an angiotensin receptor antagonist tended to reduce urine AGT concentration, but not urine MMP‐7 or gremlin‐1." (PMID 24793984, 2014). "However, the effect of SGLT2 inhibitors on urinary angiotensinogen excretion in type 2 diabetes patients has not been investigated yet." (PMID 28596160, 2017). "In patients with type 2 diabetes, treatment with SGLT2 inhibitors also tended to decrease urinary AGT excretion, although these changes were not statistically significant." (PMID 30717173, 2019). "Thus, the finding that administration of SGLT2 inhibitors did not change either total or intact angiotensinogen/creatinine ratio in the urine supports the hypothesis that intrarenal RAS is not activated by treatment with SGLT2 inhibitors in patients with type 2 diabetes." (PMID 28596160, 2017). "We also find a decrease in urine AGT, but not MMP‐7 or gremlin‐1, in response to RAS inhibition in people with type 2 diabetes and DKD, potentially reflecting therapeutic response." (PMID 24793984, 2014).
cardiomyopathy (70 papers, 2010 to 2026). A disease of the heart muscle or myocardium proper. "Extensive attention has been devoted to investigating the potential link between the AGT M235T polymorphism and the development of cardiomyopathy." (PMID 38166133, 2024). "Five studies have been conducted to investigate the relationship between AGT M235T polymorphism and the risk of cardiomyopathy." (PMID 38166133, 2024). "Results from GO_BP and AUCell analyses suggest that C3 AGT + Fibroblasts may be associated with immune response activation, protein transport, and myocardial contractile function, correlating with disease progression in cardiomyopathy." (PMID 38799173, 2024). "Therefore, C3 AGT + Fibroblasts may be associated with the progression of cardiomyopathy deterioration." (PMID 38799173, 2024). "In this meta-analysis, we reviewed all eligible studies that evaluate the associations between ACE I/D, AGT M235T, and AGTR1 A1166C gene polymorphisms and the risk of cardiomyopathy." (PMID 38166133, 2024). "The differential cellular plasticity and transcriptional regulatory activity between C3 AGT + Fibroblasts and other subgroups offer new perspectives for targeting fibroblast subpopulation activity to treat cardiomyopathy." (PMID 38799173, 2024). "The CTD database showed that the common hub genes (IGF1, MYH11, TGFB3, ALB, and AGT) were targets in cardiomyopathies." (PMID 35845066, 2022). "AGT M235T polymorphism and cardiomyopathy were not significantly correlated (allelic model T vs M: OR = 1.26, 95CI% = 0.96–1.66; dominant model TT+MT vs MM: OR = 1.30, 95CI% = 0.98–1.73; recessive model TT vs MT+MM: OR = 0.63, 95CI% = 0.37–1.07)." (PMID 38166133, 2024). "Thus, C3 AGT + Fibroblasts in the normal group had a modest correlation with other subpopulations, whereas C3 AGT + Fibroblasts after the development of cardiomyopathy lost some correlation with other subpopulations." (PMID 38799173, 2024). "Based on the single-cell characterization of cardiomyopathic fibroblasts, we conclude that C3 AGT + Fibroblasts may be more sensitive to cardiomyopathy, whereas the activity of other subpopulations may be more suppressed." (PMID 38799173, 2024). "In addition, the GO_BP enrichment results also showed that the enrichment score of the biological process of muscle contraction were higher in C3 AGT + Fibroblasts than in other cardiomyopathy fibroblast subpopulations." (PMID 38799173, 2024). "We hypothesized that the heterogeneity of C3 AGT + Fibroblasts in cardiomyopathy is more prominent, and the possibility exists with the development of cardiomyopathy." (PMID 38799173, 2024). "Moreover, correlation analysis of transcriptional regulatory activity between fibroblast subpopulations reveals a more pronounced heterogeneity within C3 AGT + Fibroblasts in cardiomyopathy." (PMID 38799173, 2024). "In this study, we conducted a systematic review and meta-analysis to summarize the findings regarding the impact of angiotensin converting enzyme (ACE) I/D, angiotensinogen (AGT) M235T, and angiotensin II Type 1 receptor (AGTR1) A1166C gene polymorphisms in patients with cardiomyopathy." (PMID 38166133, 2024). "AGT M235T polymorphism and cardiomyopathy were not significantly correlated." (PMID 38166133, 2024). "These disorders are categorized into major clinical groups, such as Skeletal Dysplasias (e.g., analysis of genes like ACAN, ACP5, and ACVR1), Osteogenesis Imperfecta (COL1A1, COL1A2, BMP1), Metabolic Disorders (ACE, AGT, BICC1), and Cardiomyopathies, among others." (PMID 40282387, 2025). "Because EPAS1 was densely and highly expressed in C3 AGT + Fibroblasts, and MYC was densely but poorly expressed in C3 AGT + Fibroblasts, whether inhibition or promotion of EPAS1 and MYC is beneficial to the treatment of cardiomyopathy requires further study." (PMID 38799173, 2024).
cardiomyopathy (continued). "Based on the findings of cell type-specific regulatory activity, the most active TFs in each of the 4 cardiomyopathy fibroblast subpopulations, including NR3C1 (C0 THBS4+ Fibroblasts), KLF4 (C1 LINC01133+ Fibroblasts), FOSB (C2 FGF7+ Fibroblasts), FOS (C3 AGT + Fibroblasts)." (PMID 38799173, 2024).
acute kidney injury (69 papers, 2008 to 2025). Sudden and sustained deterioration of the kidney function characterized by decreased glomerular filtration rate, increased serum creatinine or oliguria. "PH1 is an inherited disease characterized by increased oxalate production from accumulated glyoxylate when AGT is deficient, leading to renal failure." (PMID 22558413, 2012). "Elevated urinary angiotensinogen (UA) was identified as novel prognostic biomarker capable of predicting adverse outcomes in worsening of acute kidney injury and even need of hemodialysis therapy in intensive care unit." (PMID 24818138, 2014). "Urinary angiotensinogen/creatinine ratio was found to be higher in preterm than in full term neonates and may serve as a marker for acute kidney injury." (PMID 26719973, 2015). "Cystatin-C, angiotensinogen, NGAL, and KIM-1 are known markers of acute kidney injury." (PMID 27672664, 2016).
left ventricular hypertrophy (68 papers, 2010 to 2026). Enlargement of the LEFT VENTRICLE of the heart. "Expression of AGT T allele is also associated with left ventricular hypertrophy and enhanced production of ANG II, which mediates vascular smooth muscle growth, capillary density and oxygen consumption in muscle." (PMID 31708962, 2019). "There is a correlation between elevated levels of the cardiac renin-angiotensin system (RAS), which includes angiotensinogen, angiotensin-converting enzyme (ACE), angiotensin II, and left ventricular hypertrophy." (PMID 40463932, 2025). "The association between AGT M235T and LVM in Vietnamese hypertensive patients emphasizes once again the significant effect of this genetic polymorphism in left ventricular hypertrophy pathophysiology in Asian populations." (PMID 33681303, 2021). "Studies have demonstrated that all components of RAS (e.g., renin, angiotensinogen, ACE and AngII receptors) are identified in the heart at both the mRNA and the protein levels and that RAS is activated in experimental left ventricular hypertrophy induced by hemodynamic overload." (PMID 25739102, 2015).
ischemia (62 papers, 2007 to 2025). A hypoperfusion of the BLOOD through an organ or tissue caused by a PATHOLOGIC CONSTRICTION or obstruction of its BLOOD VESSELS, or an absence of BLOOD CIRCULATION. "In addition, in human renin and angiotensinogen double transgenic mice, the activation of human Ras enhances ischemia-induced brain injury by significantly reducing cerebral blood flow and enhancing oxidative stress." (PMID 35378910, 2022).
breast carcinoma (59 papers, 2004 to 2026). "Noting worthily, multipole investigations suggested the biomarker value of AGT polymorphisms in breast cancer as well, which implicated potential alterations in terms of expression or activity." (PMID 31142626, 2019). "Our data underlined the critical role of AGT in the tumor biology of breast cancer, which was responded to and down-regulated by high glucose and consequently contributed to the malignant proliferation and metastasis." (PMID 31142626, 2019). "Our results characterized the anti-tumor properties of AGT in breast cancer cells, which might eventually underlie the pro-tumoral effects of high glucose in this disease." (PMID 31142626, 2019). "Suppression of AGT by high-glucose treatment plays a critical role in the promotion of proliferation and metastasis in breast cancer, suggesting that AGT is a cancer suppressor gene." (PMID 40836964, 2025). "Overexpression of angiotensinogen reversed high glucose–induced proliferative and metastatic properties of breast cancer cells, highlighting how angiotensinogen can regulate the high glucose exposure in breast cancer cells." (PMID 36984785, 2023). "High glucose exposure suppressed the expression of angiotensinogen, which was completely reversed with low glucose exposure, indicating that angiotensinogen expression is subjected to a negative regulation action of glucose in breast cancer cells." (PMID 36984785, 2023). "High‐glucose levels can impair angiotensinogen and enhance breast cancer proliferation and metastasis." (PMID 32678516, 2020). "In breast cancer risk, AGT was involved in postmenopausal women, and the pro-tumor properties of high glucose in breast cancer cells are mainly attributed to inhibition of AGT." (PMID 32090070, 2020). "Our data clearly highlighted the critical roles of AGT in mediating the pro-tumoral properties of high glucose in breast cancer cells." (PMID 31142626, 2019). "A number of investigations have addressed the importance of high glucose in breast cancer, however, the involvement of angiotensinogen (AGT) in this scenario is yet to be defined." (PMID 31142626, 2019). "High AGT remarkably suppressed proliferation, inhibited viability, and compromised migration/invasion of breast cancer cells." (PMID 31142626, 2019). "Our study has characterized the pro-tumor properties of high glucose in breast cancer cells, which is predominantly attributed to the suppression of AGT." (PMID 31142626, 2019). "A high-content cytokine array ( including 308 cytokines ) analysis showed hypoxia induced an immunosuppressive cytokine profile; however, AGT silencing re-established an immune-activating cytokine profile for hypoxic 4T1 breast cancer cells." (PMID 30208943, 2018). "Our previous finding validated the tumor suppressor role of AGT in breast cancer cells, which prompted us to clarify whether suppression of AGT elicited by high glucose treatment predominantly contributed to its pro-tumoral effects." (PMID 31142626, 2019). "Therefore, our study unambiguously demonstrated the oncogenic contributions of high glucose in breast cancer cells in terms of growth and metastasis, which was predominantly mediated by the suppressive expression of AGT." (PMID 31142626, 2019). "However, AGT silencing in these cells clearly inhibited the tumor growth in 4T1 breast cancer and CT26 colon cancer in BALB/c mice with normal immune systems." (PMID 30208943, 2018). "Furthermore, adenovirus‐mediated AGT overexpression inhibits tumour growth by 70% in established human MDA‐MB‐231 breast cancer cells compared with controls, and blocks the tumorigenesis and lung metastasis of MDA‐MB‐231 and mouse melanoma B16F10 cells in C57BL/6 mice." (PMID 33511766, 2021). "Therefore, we proposed that aberrant down-regulation of AGT served as a prognostic biomarker for breast cancer, and restoration of AGT expression might be a promising therapeutic strategy in consideration of the high blood glucoses exposure of this disease." (PMID 31142626, 2019).
breast carcinoma (continued). "For RFS and DMFS in breast cancer and for DFS and DSS in colorectal cancer, AGT was a protective factor." (PMID 34671200, 2021). "Another study demonstrates that the RAS components, angiotensinogen, renin, ACE and AT1R are expressed in hormone-receptor negative and ER+ve human breast cancer tissue, as well as in representative human breast cancer cells." (PMID 28416734, 2017). "Therefore, we, for the first time, disclosed that transcription of AGT in breast cancer cells was subjected to the negative regulatory action of glucose concentration, which might consequently underlie the pro-tumoral activities of high glucose in breast cancer cells." (PMID 31142626, 2019).
coronary artery disease (55 papers, 2008 to 2025). "This study aimed to investigate the association of high cholesterol levels, and the angiotensinogen M235T (rs699) gene variant with ischemic heart disease in hypertensive patients." (PMID 40717713, 2025). "Studies of the M235T polymorphism in AGT gene and risk of coronary heart disease under additive model grouped by study characteristics." (PMID 18575631, 2008). "ORs and 95% CI for coronary heart disease and the M235T polymorphism in AGT gene under different genetic models." (PMID 18575631, 2008). "The relationship between angiotensinogen gene variations and other risk factors in ischemic heart disease (IHD) remains unclear, largely due to the complex interplay of genetic and environmental factors." (PMID 40717713, 2025). "The AGT M235T TT genotype and T allele are associated with ischemic heart disease in hypertensive patients, which may suggest as a potential biomarker for early detection and prevention." (PMID 40717713, 2025). "The single nucleotide polymorphism of AGT M235T (rs699) has been linked to the development of coronary artery diseases (CAD)." (PMID 36557328, 2022). "Within this study, we evaluated the possible association of AGT +11525C/A (rs7079) with the clinical characteristics of patients with coronary artery diseases (CAD)." (PMID 36360218, 2022). "Also, AGT polymorphism may affect restenosis after stent implantation in patients with coronary heart disease." (PMID 32667032, 2020). "It has been found that both AGT and EL genes have gene polymorphisms, which may affect gene transcription and expression, and are closely associated with the significant increase in coronary heart disease risks." (PMID 32667032, 2020). "A significant effect of gene-gene interaction in coronary artery disease was detected for G-217A and M235T of AGT gene and I/D of ACE gene." (PMID 25961019, 2015). "Most genetic associations show congruent levels of risk comparing ischemic stroke with ischemic heart disease, but three genes—glycoprotein IIIa, PAI-1 and angiotensinogen—show significant dissociations." (PMID 20161734, 2010). "Assessment of AGT, and AGRT1 gene polymorphism as a Predisposing risk for coronary artery disease." (PMID 40290236, 2025). "Angiotensinogen-235 T was present in 19% of the control population compared with 15% of the individuals in Western populations, and an association was seen between the AGT gene and the risk for coronary heart disease (CHD)." (PMID 25984491, 2014). "The interactions between T174M, M235T, G-6A, A-20C, G-152A, G-217A of AGT gene, I/D of ACE gene, and A1166C of AT1R gene have been examined in coronary artery disease." (PMID 25961019, 2015). "Metabolic risk markers and pro-inflammatory agents, including resistin, tumor necrosis factor (TNF)-α, and angiotensinogen (AGT), were similarly expressed in EAT from coronary artery disease (CAD) patients and in omental AT from non-CAD subjects." (PMID 40933307, 2025).
viral infection (55 papers, 2014 to 2025). "The key genes IL6 and AGT are involved in regulating immune response, cytokine activity, and viral infection." (PMID 35165525, 2022). "Their study disclosed that Zinc with AGT as its target protein can resist other virus infections, which was quite important for regulating immune function and reducing inflammation." (PMID 34031435, 2021).
hyperlipidemia (52 papers, 2008 to 2026). "Hyperlipidemia as a major risk factor of CAD increases the plasma concentration of angiotensinogen and the angiotensin peptides II and III and up-regulates the expression of the angiotensin II type 1 receptor (AT1R) gene." (PMID 25984491, 2014).
pulmonary hypertension (51 papers, 2010 to 2025). Increased pressure within the pulmonary circulation due to lung or heart disorder. "Furthermore, PDE4B was shown to regulate the phosphorylation and nuclear translocation of FUS, which binds to the angiotensinogen (AGT) promoter and enhances AGT expression, thereby promoting pulmonary hypertension." (PMID 41243803, 2025).
Hypercholesterolemia (48 papers, 2004 to 2025). An increased concentration of cholesterol in the blood. "The M235T polymorphism in the AGT gene has been associated to an increased CVD risk in the presence of hypercholesterolemia." (PMID 23497168, 2013).
Alzheimer disease (46 papers, 2013 to 2026). A progressive, neurodegenerative disease characterized by loss of function and death of nerve cells in several areas of the brain leading to loss of cognitive function such as memory and language. "Hyperactivation of the brain RAS has been linked to Alzheimer’s disease, yet data on the levels of AGT in the human Alzheimer’s disease brain and CSF are very limited." (PMID 37680670, 2023). "Angiotensinogen, thioredoxin-1 and interleukin-15 had the most prominent associations with Alzheimer’s disease pathology, synaptic and axonal damage markers." (PMID 37680670, 2023). "As shown in the correlation map, IL-15, TRX-1 and AGT had the highest number of significant correlations, after the core Alzheimer’s disease and synaptic biomarkers." (PMID 37680670, 2023). "Two key biomarkers of the clusters (TRX-1 and AGT) were further analysed by immunofluorescence staining of human control and Alzheimer’s disease post-mortem hippocampal tissue." (PMID 37680670, 2023). "Moreover, AGT co-localized extensively with p-tau in Alzheimer’s disease brains, further supporting its implication in the disease pathology." (PMID 37680670, 2023). "In addition, regarding neurodegenerative diseases (NDDs), several functions, including Huntington’s disease signaling (EGFR, MAPK1, PSMB3), neuroprotection by THOP1 in Alzheimer’s disease (AGT, MAPK1) and Parkinson’s signaling (MAPK1), were activated only in aged mice." (PMID 38590360, 2024). "An analysis of post-mortem hippocampal tissue showed that compared with non-demented controls, angiotensinogen staining was higher in Alzheimer’s disease and co-localized with phosphorylated-tau." (PMID 37680670, 2023).